ARL11 (ARF like GTPase 11)
Description:
May play a role in apoptosis. May act as a tumor suppressor.
Synonyms: ARLTS1; FLJ33930
Tractability: Antibody: its Gene Ontology location is reachable by antibodies, with medium confidence. PROTAC: ubiquitination databases record sites on it.
Gene: Protein-coding gene on chromosome 13 (49,628,464 to 49,634,842, forward strand). Ensembl gene ENSG00000152213.
Subcellular location (Human Protein Atlas): Cytosol; Intermediate filaments
Gene Ontology:
Molecular function: protein binding; GTP binding; GTPase activity
Biological process: intracellular protein transport
Cellular component: plasma membrane
Genetic constraint (gnomAD): Loss-of-function variants: 0 observed, 0.44 expected, observed/expected ratio (o/e) 0, 90% interval 0 to 1.84. That is too few expected variants to judge how well the gene tolerates losing a copy. Missense variants: 134 observed, 119.35 expected, observed/expected ratio (o/e) 1.12, 90% interval 0.98 to 1.3. Synonymous variants: 43 observed, 55.23 expected, observed/expected ratio (o/e) 0.78, 90% interval 0.61 to 1.
Homologues: Orthologues: chimpanzee ARL11 (99% identical), macaque ARL11 (95% identical), mouse Arl11 (78% identical), rabbit ARL11 (76% identical), rat Arl11 (75% identical), pig ARL11 (72% identical), guinea pig ARL11 (72% identical), tropical clawed frog arl11 (52% identical). Paralogues in human: ARL14 (41% identical), ARL4C (39% identical), ARF6 (38% identical), ARF3 (37% identical), ARF5 (37% identical), ARF1 (36% identical), ARF4 (36% identical), ARL3 (36% identical), ARL4A (36% identical), ARL4D (35% identical), ARL1 (34% identical), ARL2 (34% identical), and 18 more.
Diseases named in the same sentence as ARL11 in open-access papers:
ARL11 is named in the same sentence as 24 diseases in open-access papers, as found by Europe PMC text mining. Sharing a sentence is not in itself a finding about the gene and the disease. The quoted sentences say what the papers report.
breast carcinoma (6 papers, 2008 to 2023). "Researchers have demonstrated that ARL11 variants may contribute to the familial risk of various cancer types, such as chronic lymphocytic leukemia, melanoma, breast cancer, prostate cancer, colorectal cancer, and ovarian cancer." (PMID 36367890, 2022). "Notably, another member of this family, ARL11 (ARLTS1), is a tumor suppressor gene where truncating germline mutations or promoter methylation contribute to leukemia, breast cancer, ovarian cancer, and melanoma." (PMID 18485879, 2008). "ARL11, also known as ADP Ribosylation factor-Like Tumor Suppressor gene 1 (ARLTS1) was described as a potential low-penetrance tumor suppressor gene in different types of cancers, such as breast cancer, melanoma and chronic lymphocytic leukemia." (PMID 32426352, 2020).
prostate carcinoma (6 papers, 2011 to 2023). A carcinoma that arises from epithelial cells of the prostate gland. "While in CM ARL11 was found upregulated, compared to normal skin tissue, in breast, lung, ovarian and prostate cancers, it was shown to be downregulated by DNA hypermethylation and genomic deletions." (PMID 34502169, 2021).
colorectal cancer (5 papers, 2011 to 2023). A primary or metastatic malignant neoplasm that affects the colon or rectum. "The evidence that germ-line polymorphisms in the ARL11 sequence were associated with familial risk for CLL and for breast, prostate, and colorectal cancers supported a causal role for ARL11 in carcinogenesis (9, –, 15)." (PMID 29618517, 2018).
lung carcinoma (5 papers, 2011 to 2023). "Subsequent studies reported down-regulation of ARL11 expression in several sporadic lung cancer and ovarian tumors attributed to promoter methylation and loss of heterozygosity at the ARL11 gene locus." (PMID 29618517, 2018). "Consistently, a previous study proposed ARL11 as a tumor suppressor gene due to its ability to inhibit tumor formation in immunodeficient mice after transfection with a lung cancer cell line." (PMID 34502169, 2021). "On the other hand, ectopic expression of ARL11 in lung carcinoma was reported to induce apoptosis, suggesting that ARL11 down-regulation promotes tumor cell survival." (PMID 29618517, 2018).
familial cancer (2 papers, 2009 to 2017). "Insertions in integrin alpha 9 (ITGA9), located in a region of frequent homozygous deletions in tumor samples, and ADP-ribosylation factor-like 11 (ARL11), a genetic variant of which predisposes to familial cancer, were detected in the early phase, but never among the late phase samples." (PMID 19148292, 2009).
Obesity (1 paper, 2022). Accumulation of substantial excess body fat. "It remains to be investigated whether Arl11 may take a causal role in this scenario or whether increased mRNA expression in NZO gWAT rather occurs secondarily as a consequence of obesity-induced inflammation." (PMID 35796564, 2022).
Salmonella Infections (1 paper, 2018). Infections with bacteria of the genus SALMONELLA. "Unlike the Salmonella-infected control shRNA–treated cells, where transient but substantial phosphorylation of ERK1/2 and p38 MAPKs was observed, ARL11-depleted cells had impaired MAPK activation in response to Salmonella infection (quantification shown in b and c)." (PMID 29618517, 2018).
tumor (14 papers, 2008 to 2025). "It has been suggested that ARL11 SNPs, especially rs3803185, may act as low penetrance variants in several neoplasms including CRC." (PMID 21819567, 2011). "In contrast, the higher the expression of ARL5A and ARL11 genes, the lower the sensitivity to tumor-targeted drugs." (PMID 35774359, 2022). "ARLTS1/ARL11 was initially identified as a tumor suppressor at the gene locus 13q14.3, a region frequently deleted in a variety of hematopoietic and solid tumors." (PMID 29618517, 2018). "ARL11 was first identified in a screening for putative tumor suppressor genes at chromosome location 13q14.3, a region frequently deleted in a variety of sporadic and hereditary hematopoietic and solid tumors (3, –, 6)." (PMID 29618517, 2018). "For example, ARL11, a gene with recently identified tumor suppressor function, was up-regulated after both inhibiting PI3K and suppression of p70S6K." (PMID 18652687, 2008). "Further functional analysis showed that ARL11’s prognostic role may result from its promotion of tumor immunosuppression." (PMID 36367890, 2022). "In brief, function enrichment analysis and correlation analysis indicated that the prognostic value of ARL11 may result from its role in enhancing tumor immunosuppression." (PMID 36367890, 2022). "In familial breast cancer and CM, ARL11 was suggested as a low-penetrance tumor suppressor gene." (PMID 34502169, 2021). "However, the bioinformatics analysis performed highlighted the essential role of the tumor microenvironment in the mechanisms related to the prognostic value of ARL1 expression but mostly ARL11 expression." (PMID 34502169, 2021). "However, as most studies on this putative tumor suppressor involved ectopically expressing the protein in tumor cell lines, the endogenous function of ARL11 has remained uncharacterized so far." (PMID 29618517, 2018). "As tumor immunosuppression is a critical step of preinvasive-to-invasive transition and relates to poor prognoses in BC, we speculate that the prognostic role of ARL11 in BC may be due to its function in boosting tumor immunosuppression." (PMID 36367890, 2022). "Thus, forced ARL11 expression in tumor cells might promote sustained ERK1/2 activation, resulting in up-regulation of apoptotic markers." (PMID 29618517, 2018). "ARL11, which is also named ADP-ribosylation factor-like tumor suppressor gene-1 (ARLTS1), was initially described as a tumor suppressor." (PMID 38533085, 2024). "Despite its controversial function, P2RX7, a plasma membrane receptor for extracellular ATP that is expressed at a high level by immune and tumor cells, also belongs to the PPI network of ARL11 (score = 0.7)." (PMID 34502169, 2021). "One low-penetrant candidate gene is ARLTS1 (ARL11), ADP-ribosylation factor like tumour suppressor protein 1, a putative tumour-suppressor gene on chromosome 13q14, which has been shown to function in many human cancers." (PMID 23940804, 2013). "This role of ARL11 was not specific to macrophages, as ectopic expression of ARL11 in tumor cell lines was sufficient for ERK1/2 activation, an effect not observed upon transfection of other ARL family members." (PMID 29618517, 2018). "ARL11, also known as ARLTS1 (ADP-ribosylation factor-like tumor suppressor gene 1), is a tumor suppressor gene that belongs to the ARF family of the Ras superfamily of small GTPases that are known to be involved in multiple regulatory pathways altered in human carcinogenesis." (PMID 21819567, 2011). "Since CM is a highly immunogenic type of tumor, after discovering that ARL1, ARL11, and ARL15 expression may have a significant impact on CM patients’ prognosis, we investigated whether the immune microenvironment could be involved in the mechanisms associated with ARL prognostic value." (PMID 34502169, 2021).
cancer (10 papers, 2008 to 2025). A tumor composed of atypical neoplastic, often pleomorphic cells that invade other tissues. "Further functional enrichment analysis demonstrates that ARL11 enhances the immunosuppression in BC, and dysregulation of ARL11 is significantly associated with immune infiltration in various types of cancer." (PMID 36367890, 2022). "ADP-ribosylation factor-like GTPase 11 (ARL11) is a cancer-predisposing gene that has remained functionally uncharacterized to date." (PMID 29618517, 2018). "In addition, we investigated the relationship between ARL11 expression and immune infiltration in pan-cancer and found that dysregulation of ARL11 was significantly associated with immune infiltration in various cancer types." (PMID 36367890, 2022). "ARL11 was initially identified as a low-penetrance cancer gene at the chromosome 13q14.3 that gets continually deleted in some hematopoietic and solid tumors." (PMID 36367890, 2022). "Altogether, these results indicate that ARL11 upregulation has a positive impact in CM patients’ overall survival, in part by inducing an immune profile relying on an anti-cancer activity to a greater extent compared to ARL1 expression." (PMID 34502169, 2021). "Genes associated with MAPK regulation, caspase activation, and tumorigenesis are also part of the ARL11 interactive network, highlighting its pivotal role in the regulation of immune and cancer-related pathways." (PMID 34502169, 2021). "Our findings also explain the previously established role of ARL11 in promoting cancer cell apoptosis." (PMID 29618517, 2018). "Our enrichment analysis demonstrated that ARL11 expression is involved in several immunosuppressing processes in BC, including T cell differentiation and PD-L1 expression and the PD-1 checkpoint pathway in cancer." (PMID 36367890, 2022).
infection (1 paper, 2018). The state of being infected such as from the introduction of a foreign agent such as serum, vaccine, antigenic substance or organism. "We next investigated whether ARL11 is required for macrophage activation upon infection with live bacteria and for subsequent bacterial clearance by activated macrophages." (PMID 29618517, 2018).
ARL11 also shares sentences with these, for which no sentence is quoted: ovarian carcinoma (5 papers); chronic lymphocytic leukemia (4); melanoma (4); prostate tumors (2); basal cell carcinoma of the skin (1); benign prostatic hyperplasia (1); depression (1); hereditary prostate cancer (1); laryngeal carcinoma (1); leukemia (1); ovarian tumors (1); thrombosis (1); thyroid cancer (1); thyroid papillary cancer (1).